PRL (prolactin)
Diseases named in the same sentence as PRL in open-access papers (continued):
Sharing a sentence is not in itself a finding about the gene and the disease.
tumor (continued). "In EC, DSCAM-AS1 was associated with endometrial tumor promotor gene PRL and with expression of ERα and its target genes TFF1 and PGR." (PMID 35885035, 2022). "The hook effect is responsible for the discrepancy between tumor size and PRL levels, which generally requires a further diagnostic step based on serum sample dilution." (PMID 36237192, 2022). "The hormone deficiency usually improves after normalization of PRL and reduction of tumor size in patients with macroprolactinomas." (PMID 34771538, 2021). "Beside the well known function of PRL in mammary gland development and lactation, PRL stimulates proliferation of different cell types in the body and has been linked to enhanced tumor cell growth." (PMID 34358244, 2021). "The third frontal craniotomy and subtotal removal of the tumor were performed, the symptoms of vision loss were improved significantly, and the serum prolactin levels decreased to 108.0 ng/mL." (PMID 34715828, 2021). "For now, what has been unequivocally established is that prolactin has direct effects on tumor Tregs that cause them to promote EMT." (PMID 34375938, 2021). "During postoperative follow-up, she experienced acute right vision loss, and MRI reported a rapidly enlarged tumor with compression of the optic chiasm, and the serum prolactin levels increased to 356.0 ng/mL again." (PMID 34715828, 2021). "The tumor was subtotally removed, the symptoms of vision loss improved significantly after surgery, and the serum prolactin levels decreased to 356.0 ng/mL." (PMID 34715828, 2021). "Among these, PRL/PRLR was observed to have a specific association with tumor fibrosis, and PRLR was confirmed by IHC (n = 68, rho = −0.281, p = 0.020)." (PMID 34539753, 2021). "Preoperative serum prolactin concentrations were positively associated with maximum tumor diameter (r = 0.649, p < 0.001), Knosp grade (U = 77.0, p = 0.004), and patient age (r = 0.571, p < 0.001)." (PMID 32733387, 2020). "Altogether, we investigated the genomic and transcriptomic correlation in PAs in the present study and demonstrated for the first time that high CNVs in PRL-PAs play an important role in tumor development and are significantly associated with poor prognosis." (PMID 33472173, 2020). "Nevertheless, the combination of S179D PRL and the highest dose of calcitriol for only 28 days caused 50% of the tumor volume to become entirely acellular." (PMID 33179012, 2020). "These neoplasms arise from the lactotroph cells and—as their name suggests—produce PRL, which can then cause endocrine imbalance including amenorrhea, infertility, or galactorrhea." (PMID 31818039, 2019). "Cabergoline is effective in normalizing prolactin concentrations in 80% of patients resistant to bromocriptine and causes tumor size reductions in 70% of them." (PMID 30542321, 2018). "The results of the present study demonstrated that high preoperative PRL levels, large tumor volumes, and invasive prolactinomas were associated with persistent disease, in multivariate analysis, and influenced postoperative improvement." (PMID 30407358, 2018). "Univariate analysis demonstrated that the defect of postoperative recovery was associated with tumor size, preoperative PRL levels, and invasion of prolactinomas." (PMID 30407358, 2018). "Cystic prolactinomas constitute another potential cause of discrepancy between the prolactin serum level and tumor volume since, although the tumor volume is large, the number of viable cells is low due to cystic degeneration." (PMID 27533614, 2016). "A recent study on macroprolactinomas in children and adolescents indicated that DA resistance is associated with higher PRL levels and larger tumor sizes, which are closely linked together." (PMID 27999593, 2016). "Previously, greater expression of PRL has been associated with progression of tumour development in different cancers." (PMID 26798410, 2016).
tumor (continued). "A decrease in number or function of D2Rs would be the cause of the discordance observed between PRL levels and tumor size." (PMID 26909481, 2016). "The patient should be informed about the relatively higher risk of tumor enlargement, the need for normalization of prolactin, and the importance of treatment before conception." (PMID 26074878, 2015). "The association of PRL and its receptor with tumor progression was first established on animal models many decades ago." (PMID 26346346, 2015). "On the other hand, there is no data to suggest breastfeeding is associated with an increased prolactin production or risk of tumor enlargement." (PMID 26074878, 2015). "It has been documented that the activated signaling by PRL/PRLR is associated with tumor development." (PMID 26346346, 2015). "Recent studies have suggested an association of PRL with tumor proliferation, evidencing the hormone as an antiapoptotic or mitogenic factor." (PMID 23317095, 2013). "In five studies that prospectively investigated tumour shrinkage during Cabergoline therapy tumour shrinkage was associated with a higher baseline PRL and IGF-1 concentration." (PMID 22550484, 2012). "Transcript analysis demonstrates that many of these carcinomas express the ERα-associated transcript signature that defines this clinical tumor subtype, and suggests that they arise from the physiologic target cells of PRL." (PMID 21276249, 2011). "Although the relationship between circulating PRL and patient survival has been examined only in smaller studies, higher levels have been associated with tumor aggression, higher risk of metastasis and poor long term survival." (PMID 21276249, 2011). "We further evaluated the association of PRL levels with clinically important tumour characteristics among cases." (PMID 20736944, 2010). "Accordingly, further assessment of risk related to PRL levels by patient and tumour characteristics is needed." (PMID 20736944, 2010). "This difference in PRL levels translated into a stronger risk association for lobular (OR=3.04, 95% CI: 1.81–5.91) than ductal (OR=1.62, 95% CI: 1.18–2.23) tumours." (PMID 20736944, 2010). "Crossing prolactin-deficient mice with oncogenic polyoma middle-T antigen transgenic mice demonstrated that prolactin decreased the latency of tumour formation and increased tumour growth." (PMID 19014541, 2008). "Additionally, measuring IPS prolactin (PRL) levels has been proposed to enhance the diagnostic accuracy of tumor laterality." (PMID 41287677, 2025). "Together, these data indicate that surgery could significantly decrease both systolic and diastolic BP, which were highly associated with the subdivided variables of age, sex, tumor size, invasion, resistance to DA, recurrence, and preoperative PRL levels." (PMID 38398117, 2024). "The role of CNNM4 in cancer may be linked to its association with PRL, which promotes Mg2+ accumulation intracellularly, thereby supporting tumor growth and metastasis." (PMID 39691602, 2024). "Similarly, in human studies, in which the expression of the ErbB receptors was correlated with the clinical tumor behavior, revealed that ErbB2 was mainly associated with aggressive and/or resistant prolactin-secreting PitNETs." (PMID 37109772, 2023). "This retrospective cohort study conducted among 44 patients who underwent TSS due to non-functional pituitary macroadenoma indicated post-operative TSH and prolactin levels are more likely to be associated with some MRI characteristics before surgery namely size and volume of the tumor." (PMID 35365091, 2022). "Cabergoline normalizes prolactin in up to 85% of patients and causes tumor shrinkage in up to 80%." (PMID 36013562, 2022). "We further measured the protein chips of 640 cytokines in ccRCC specimens and found that several cytokines, including prolactin (PRL), were associated with the degree of fibrosis in the tumor, as confirmed by the prolactin receptor (PRLR) immunohistochemical method." (PMID 34539753, 2021).
tumor (continued). "Importantly, high prolactin levels were associated with a 60% increased risk of estrogen receptor positive tumor." (PMID 34206988, 2021). "Consequently, glucocorticoid negative feedback on synthesis, and consequently, secretion of PRL is deficient in pituitary-tumor-bearing rats." (PMID 32188093, 2020). "In established carcinomas, however, prolactin may facilitate tumor differentiation and thus it may reduce metastatic risk." (PMID 31581718, 2019). "Germline mutations in the MEN1 tumor-suppressor gene have been found in PRL-secreting tumors." (PMID 31818039, 2019). "Resistance to DA is associated with higher prolactin levels and larger tumour size." (PMID 30014342, 2018). "Consistent with the current analysis, recent results from the Nurses’ Health Study suggest that prolactin primarily plays a role in the late stage of tumor development, with stronger positive associations observed among participants providing blood samples closer to diagnosis." (PMID 25887963, 2015). "Thus, it has been reported that bromocriptine decreases prolactin serum levels in Prlr mutant mice harboring tumors and reduces tumor cell proliferation in p27Kip1 deficient mice." (PMID 25136513, 2014). "However goserelin administration achieves regression in tumour development associated to inhibition PRL, TNF alpha and NO expression." (PMID 18045456, 2007). "Additionally, a higher PRL level was associated with a more aggressive tumor." (PMID 40160874, 2025). "Higher baseline tumor volume was significantly associated with optic chiasm compression (OR = 1.002, 95% CI 1.001 – 1.003, p=0.04), sphenoid sinus invasion (OR = 1.00, 95% CI 1.00 – 1.001, p=0.04), elevated baseline PRL levels (β=0.50, p=0.008), and male sex (β=0.52, p<0.0001)." (PMID 40995599, 2025). "As the cysteine-phosphorylated forms of the proteins should persist for days in vivo, they may be useful tools for understanding the physiological function of PRL phosphorylation in magnesium homeostasis and tumor-associated signaling pathways that drive metastasis." (PMID 40398601, 2025). "The treatment primarily aims to normalize or reduce prolactin hormone levels, decrease tumor size, improve focal neurologic symptoms caused by compression, achieve eugonadism by normalizing testosterone levels, and restore the hormonal axis affected by the tumor." (PMID 37404423, 2023). "The larger tumors in males with higher prolactin levels suggest that the size discrepancy in tumors between sexes is not primarily due to a diagnostic delay, but rather reflects gender-related differences in tumor behavior, potentially involving the estrogen receptor pathway." (PMID 37664314, 2023). "This may be caused by the pituitary stalk effect; that is, when the tumour compresses the pituitary stalk, the secretion of PRL inhibitor release is blocked, and the inhibition of hypothalamus secretion of PRL is weakened, resulting in an increase in PRL." (PMID 34248835, 2021). "Finally, treatment duration of DAs were more than 24 months in all the studied included, which implicated that longer duration of normal prolactin level may help to decrease the possibility of tumor relapse." (PMID 34774043, 2021). "It has also been proposed that changes in circulating prolactin may cause animal tumor findings." (PMID 34300305, 2021). "primary cultures of human lactotroph tumor cells were transfected with an adenovirus vector containing a cDNA encoding a human tyrosine hydroxylase: transfection induced increased production of dopamine, resulting in the predicted biologic effect of decreased prolactin secretion." (PMID 32201880, 2020). "In addition, we examined the association of serum PRL levels with tumour characteristics." (PMID 20736944, 2010). "After 6 months of treatment, 24.7% achieved PRL normalization, and 29.4% demonstrated ≥ 50% reduction in tumor volume." (PMID 41595768, 2026).
tumor (continued). "Prolactinomas are exquisitely sensitive to the effect of dopamine agonists (DA), and treatment leads to tumor shrinkage and normalization of prolactin levels in approximately 80–95% of patients." (PMID 41524959, 2026). "In a recent study, a weak correlation between serum prolactin levels and maximum tumour diameters in patients with NF‐PitNETs was described." (PMID 41351299, 2026). "Prolactin levels and tumor size decrease most rapidly during the first 6 months of treatment, and the decline of prolactin levels typically precedes tumor shrinkage." (PMID 41017446, 2026). "In parallel, PRL has been detected in tumor samples from CRC patients, where increased expression correlated with more differentiated tumors, suggesting paracrine/autocrine signaling activity." (PMID 41501898, 2026). "Effects of harbouring a SCT, gender, age at surgery, preoperative tumour volume, Knosp ≥ 3 and preoperative prolactin elevation on postoperative pituitary failure." (PMID 41351299, 2026). "Case reports describing tumor enlargement despite declining prolactin levels concern macro- and giant prolactinomas treated with either bromocriptine or cabergoline." (PMID 41017446, 2026). "Resistance was defined as failure to normalize serum prolactin concentration (PRL) or achieve ≥ 30% reduction in tumor maximal diameter after standard DA therapy." (PMID 41595768, 2026). "This comprehensive study advances our understanding of GH&PRL-Pas and these results reinforce the importance of individualized treatment strategies, integrating tumor characteristics and patient-specific factors to optimize clinical outcomes." (PMID 40590355, 2025). "In a significant number of cases, a dissociation between the effect of DA treatment on PRL level and tumor shrinkage was observed." (PMID 41184667, 2025). "DA resistance was defined as the failure to normalize PRL levels and to achieve at least a 50% reduction in the tumor’s major diameter or volume." (PMID 40995599, 2025). "When IPSS results contradict suspected tumor laterality based on advanced MRI findings, a comprehensive surgical strategy should be developed that considers PRL levels obtained via simultaneous sampling." (PMID 41287677, 2025). "Dopamine agonists (DAs) normalize prolactin levels and reduce tumor mass in most patients with prolactinomas, including those with large tumors and visual defects." (PMID 41199869, 2025). "For prolactinomas, dopamine agonists such as cabergoline are indicated as the first-line treatment to control prolactin levels and reduce tumor size." (PMID 40960781, 2025). "Accordingly, in the three patients described here the macroprolactinoma quickly responded to cabergoline treatment with decreased serum prolactin levels and significant tumor shrinkage." (PMID 40327154, 2025). "Synthesis of results from previous studies have demonstrated that DA therapy leads to tumour shrinkage in 20 to 100% (median 62%) and normalization of serum prolactin in 40 to 100% (median 68%)." (PMID 40004619, 2025). "Although prolactin levels generally parallel tumor size and patients with prolactin concentrations greater than 250 μg/liter do often have a prolactinoma, this is not always true." (PMID 40255723, 2025). "These drugs reduce PRL secretion and typically induce a marked decrease in tumor size in most cases, thereby avoiding the inherent risks of neurosurgical intervention." (PMID 40599499, 2025). "Imaging demonstrated an increase in tumor size to 2.8 × 3.9 cm, with a prolactin level of 2700 ng/mL (57446.80 mIU/L)." (PMID 41013821, 2025). "In patients with clear tumor masses, which are often dismissed clinically as “PRLomas,” it is critically important for the diagnostician to analyze PRL levels in the context of tumor size." (PMID 40718390, 2025).
tumor (continued). "After 5 years of cabergoline treatment, the PRL level decreased to 106.65 ng/ml (normal values: 2.76–19.64) under 5 mg of cabergoline per week, and MRI revealed necrosis of the residual tumor mass (11/10/11 mm) with retrosellar extension." (PMID 40160874, 2025). "Individuals who did not achieve remission exhibited a more pronounced elevation in serum PRL for each increment in preoperative tumor volume, suggesting the presence of distinctive tumor characteristics." (PMID 39904877, 2025). "In long-term follow-up, growth and puberty have been shown to resume normally after PRL control and tumor reduction." (PMID 40599499, 2025). "The ErbB receptor family (EGFR, HER2, ErbB3, ErbB4) is expressed in lactotroph cells, promoting prolactin secretion, and inhibiting these receptors can lead to tumor regression." (PMID 41013821, 2025). "Its effects are likely mediated by vascular mechanisms and the presence of prolactin-specific receptors within tumor tissue." (PMID 41375054, 2025). "We showed that deguelin concentration-dependently inhibited cell viability, proliferation and prolactin secretion, and promoted apoptosis and cell cycle arrest in two prolactinoma tumor cell lines GH3 and MMQ." (PMID 41184622, 2025). "Recent studies focusing on macroprolactinomas have shown that early tumor shrinkage—assessed within 3 to 12 months—is a stronger predictor of long-term response than baseline tumor size or prolactin levels." (PMID 40995599, 2025). "Considering the response to the treatment, we evaluated the predictors of PRL levels normalization and tumor shrinkage, in terms of >50% diameter or volume decrease." (PMID 40995599, 2025). "Cabergoline-induced CSF leakage represents a potential side-effect of an excellent dopamine agonist response with major reduction in tumor size and serum prolactin level." (PMID 40327154, 2025). "Quantitative comparisons demonstrated significant reductions in GH, IGF-1, and PRL levels following tumor resection." (PMID 41470032, 2025). "Three months later, his follow-up serum PRL had decreased to 1233 ng/mL (SI: 26136.6 mIU/L), with the trend of PRL, while imaging revealed a reduction in tumor size to 3.6 × 2.2 cm." (PMID 40236612, 2025). "The failure to bring prolactin into normal range or resolve the tumour radiologically is what qualifies this as a case of cabergoline resistance." (PMID 41322860, 2025). "Considering the importance of tumor size and prolactin normalization for the recovery of pituitary dysfunction, timely and adequate treatment is fundamental." (PMID 40035956, 2025). "Prolactin levels correlated with tumor maximum diameter, more stronger in aggressive cases (r = 0.68; p = 0.047)." (PMID 41219436, 2025). "Following discontinuation of cabergoline, the patient has been on continued surveillance of his prolactin levels and tumor status, with symptomatic treatment of his UIP." (PMID 40236612, 2025). "Markedly elevated prolactin levels—closely correlated with tumor diameter—as well as visual disturbances and TSH/ACTH deficiencies should raise clinical suspicion of aggressive disease." (PMID 41219436, 2025). "A considerable number of tumors immunopositive for more than one hormone (including associations between GH/PRL, but also unusual combinations like GH/ACTH) also contained FS cells (p < 0.01), suggesting their involvement in tumor lineages differentiation." (PMID 40643539, 2025). "In 1981, a prospective study of eight patients with macroprolactinomas demonstrated reduction or normalization of serum prolactin as well as regression in tumour size following three months of bromocriptine treatment." (PMID 40004619, 2025). "Diagnosis typically hinges on elevated serum prolactin levels while other pituitary axes are within normal limits, substantiated by imaging modalities such as MRI or CT scans to ascertain tumor presence and size." (PMID 41013821, 2025).